PBRM1 (polybromo 1)
Diseases named in the same sentence as PBRM1 in open-access papers (continued):
Sharing a sentence is not in itself a finding about the gene and the disease.
cancer (continued). "We compared these lists of human genes with the DEGs found in the Chowdhury study and found that 11.2% of the cluster C and F homologs were regulated by PBRM-1 in cancer cell lines." (PMID 32957927, 2020). "Available PBAF complex mutations included PBRM1 and ARID2, present at 7.4% and 6.5%, respectively, across the pan-cancer cohort; LOF frequencies are 3.9% and 2.3%, respectively." (PMID 32820162, 2020). "Compared with other cancer types, KIRC and CHOL showed higher frequencies of PBRM1 mutations (40.1% in KIRC and 19.4% in CHOL vs. an average of 2.3% among other cancer types)." (PMID 30760718, 2019). "Given the central role of PBRM1 in oncogenesis, and the lack of information regarding its behavior in PCa, we conducted experiments to elucidate the relevance of PBRM1 as a putative cancer driver in PCa." (PMID 31212728, 2019). "Other epigenetic modifiers were also associated with high levels of ITH in KIRC (e.g., PBRM1 or KDM5C), but correlated with lower heterogeneity in a pan-cancer analysis or in other cancer types." (PMID 30897760, 2019). "By analyzing TMAs containing patients’ PCa samples, we identified PBRM1 expression in nuclei, cytoplasm, and membrane of cancer cells." (PMID 31212728, 2019). "One of the previous findings that motivated this study is that PBRM1 can be found to be differentially regulated in cancer." (PMID 31212728, 2019). "PBRM1 was recently shown to inhibit activation of IFN-stimulated genes in cancer cells in response to IFN-γ produced by T cells." (PMID 31113486, 2019). "PBRM1 is found to mediate gene regulation of cell growth, migration, proliferation and differentiation in multiple cancer types including kidney, bladder, and breast." (PMID 27556922, 2016). "This analysis shows that the 1CT7 specific mutated genes are altered in 30.4% of all CRC cases whereas A1309 specific mutated genes are altered in 73.6% of all CRC cases, among which five genes are known cancer genes, i.e. PBRM1, MYB, PRDM16, BCR and NUP214." (PMID 25923178, 2015). "To examine the potential role of PBRM1 in tumorigenesis, we first evaluated the effect of PBRM1 on the growth and clonogenicity of cancer cells in vitro." (PMID 25978027, 2015). "Two important SWI/SNF complexes implicated in cancer are the BAF and PBAF complexes, which contain the mutually exclusive ARID1A or ARID1B subunits and PBRM1 or BRD7 subunits, respectively." (PMID 24622842, 2014). "ATRX, ARID1A, PBRM1, and SMARCA4 are also among the most frequently mutated chromatin factors in cancer, and are all components of the chromatin remodeling complex SWI/SNF, which has been shown to facilitate double-strand break repair." (PMID 25484917, 2014). "It is evident from the data that genes such as VHL, TTN, BAP1, PBRM1, and SETD2 are consistently identified as the most frequently mutated genes in KIRC, underscoring their potential importance as key drivers of tumorigenesis in this specific cancer subtype." (PMID 40649942, 2025). "PBRM1 is one of the most frequently altered genes in cancer." (PMID 40093909, 2025). "Furthermore, we elucidated the regulatory mechanism of AS in PBRM1 and its impact on clinical outcomes in patients with cancer." (PMID 39375538, 2024).
cancer (continued). "While progress is being made with monotherapies, combination immune therapies with immune checkpoint inhibitors are also being studied for use with mSWI/SNF mutations, particularly with ARID2, polybromo 1 (PBRM1), ARID1A, and SMARC1B in cancer (Mittal and Roberts 2020)." (PMID 38914477, 2024). "The Tm of an isolated PBRM1 bromodomain may therefore be a sufficient proxy for the overall stability of full-length PBRM1 protein in cells, providing key mechanistic information for patient diagnosis and treatment in the context of cancer." (PMID 38460939, 2024). "In addition to protein stability and Kac binding, this study explored the impact of cancer-associated PBRM1-BD4 missense variants on nucleic acid binding and PBRM1-mediated transcriptional regulation." (PMID 38460939, 2024). "The role of PBRM1 in the resistance of cancer cells to immune cells remains debatable." (PMID 39375538, 2024). "In pan-cancer cohorts, we discovered that patients carrying POL &PBRM1 mutations may have better responses to ICIs." (PMID 39218995, 2024). "Higher TMB in these three cancer types with POL&PBRM1 mutation was observed both in the EDM group and non-EDM group compared to those with POL-o." (PMID 39218995, 2024). "We next analysed whether the AS pattern of PBRM1 E27 affects clinical outcomes of cancer patients treated with immune checkpoint inhibitors." (PMID 39375538, 2024). "Therefore, our findings provide an important key to resolve discrepancies in PBRM1 function reported in previous studies and shed light on the importance of AS patterns of PBRM1 E27 in cancer." (PMID 39375538, 2024). "Here, although we focused on the impact of PBRM1 E27 AS on patients with ccRCC treated with nivolumab, we also uncovered the diverse frequency of E27 inclusion rates in PBRM1 transcripts in individual TCGA cancer tissues; these changes also vary between different cancer types." (PMID 39375538, 2024). "Thus, we further analysed TCGA database and focused on patients with KIRC, which only showed widely distributed PSI values of PBRM1 E27 in cancer tissues between 15 cancer types." (PMID 39375538, 2024). "Notably, genes encoding PBAF and ncBAF components such as PBRM1, ARID2, BICRAL (GLTSCR1L) and others were found to be more frequently mutated in cancer than in NDD." (PMID 37500730, 2023). "PBRM1 status has also been associated with responsiveness to ICIs in selected cancers and not others." (PMID 36445328, 2023). "Furthermore, we separately assessed the PBRM1 expression of the endothelial cells and evaluated the correlation between the expression of cancer cells and endothelial cells." (PMID 35205810, 2022). "Next, we semiquantitatively assessed PBRM1 IHC expression in cancer cells using an H-score." (PMID 35205810, 2022). "Furthermore, we separately evaluated the PBRM1 expression of the vascular endothelial cells and examined the PBRM1 expression profiles of cancer cells and endothelial cells." (PMID 35205810, 2022). "We report AU-15330 as a novel, highly specific and VHL-dependent PROTAC degrader of SWI/SNF ATPase components (SMARCA2, SMARCA4 and PBRM1) that shows preferential cytotoxicity in enhancer-binding transcription factor-addicted cancers at low nanomolar concentrations." (PMID 34937944, 2022). "In vitro cell experiments showed that downregulation of PBRM1 expression could significantly promote the cancer progression and epithelial‐to‐mesenchymal transition via the PBRM1‐c‐JUN‐VIM axis." (PMID 36178086, 2022).
cancer (continued). "In our study, the relationship between PBRM1 and the prognosis of immunotherapy in pan-cancer was comprehensively analyzed by combining the universal carcinomatous public cohort and our clinical data collected in the First Affiliated Hospital of Nanjing Medical University." (PMID 36699446, 2022). "Our PBRM1 expression profile indicated that PBRM1 expression in both cancer and endothelial cells may be regulated in an orchestrated manner." (PMID 35205810, 2022). "The inactivation of PBRM1 has been reported to occur frequently in cancers." (PMID 36361605, 2022). "These observed phenotypic changes reflected that silencing PBRM1 could promote cancer cell progression and epithelial‐to‐mesenchymal transition (EMT)." (PMID 36178086, 2022). "The present study evaluates the association of architectural patterns with the PBRM1 expression of cancer cells using a cohort of 425 patients with nonmetastatic ccRCC." (PMID 35205810, 2022). "Moreover, PBRM1-defective cancer cells were sensitive to PARP and ATR inhibitors in preclinical models." (PMID 36138075, 2022). "A number of cancer-derived nonsense mutations resulted in truncations of PBRM1 that lack of CTDPBRM132, consistent with the importance of CTDPBRM1 in assembly and function of PBAF complex." (PMID 36496390, 2022). "Although previous studies have reported the possible association of PBRM1 with immune response, the specific role of PBRM1 in the pan-cancer with immunotherapy remains not thoroughly confirmed." (PMID 36699446, 2022). "In the present study, we aimed to evaluate whether the histomorphological features of ccRCC correlate with the PBRM1 expression of cancer cells." (PMID 35205810, 2022). "PBRM1 alterations also represent significant poor prognostic factors for skull-base chordomas, as observed in ccRC, reinforcing the overlap between these two cancers." (PMID 35326637, 2022). "In this study, we described the mutational landscape and the unique molecular characteristics of DPC, especially PBRM1‐inactivating mutations and the PBRM1‐c‐JUN‐VIM axis, which serve as important methods of cancer invasion and were associated with poor patient outcomes in DPC." (PMID 36178086, 2022). "In line, detailed survival analysis in our cohort indicated significantly worse cancer-specific survival probability for patients with metastases harbouring multiple somatic drivers and VHL wildtype alleles compared to PBRM1, SETD2, and VHL monodrivers (p (logrank) = 0.03)." (PMID 34944839, 2021). "As STATs are key transcription factors in cancer inflammation and immunity, the activation of STAT pathway due to the combined loss of VHL and PBRM1 could render the resulting tumors prone to immune regulation." (PMID 32743344, 2020). "In addition, somatic mutations in cancer cells, including loss-of-function mutations in JAK1/2, APLNR, PTPN2, and PBRM1, significantly correlate with the efficacy of cancer immunotherapies." (PMID 32244804, 2020). "However, it has been reported that inactivating mutations in SWI/SNF subunits (ARID1A, PBRM1, SMARCB1, and SMARCA4) also sensitize cancer cells to T cell-mediated destruction." (PMID 32649682, 2020). "Fortunately, there are less significantly mutated genes in ccRCCs compared with other cancers; the top four most commonly mutated genes are von Hippel-Lindau (VHL) tumor suppressor gene, polybromo-1 (PBRM1), BRCA1-associated protein 1 (BAP1), and SET domain containing 2 (SETD2)." (PMID 32185138, 2020).
cancer (continued). "Promising targets for potentially interesting inhibitors are the proteins of the JAK/STAT, Wnt/β-catenin, Hedgehog and Notch signalling pathways, inhibitors that target mutations in chromatin-remodelling genes, such as ARID1A, PBRM1, and BAP1, and inhibitors of cancer-associated fibroblasts." (PMID 32423017, 2020). "However, the addition of PBRM1 mutation to BAP1 mutation, which did correlate with a poor prognosis, increased the risk of cancer death (HR 4.18)." (PMID 31861590, 2019). "Our pan-cancer tissues models performed poorly when predicting PBRM1 with a ROC AUC score of 0.47." (PMID 31744086, 2019). "Cancer cellfractions were higher for the broad or arm-level loss of chromosome 3 than forBAP1 mutations, followed by PBRM1mutations, suggesting that these events occur chronologically (3p loss,BAP1, PBRM1) in CCA development." (PMID 28297679, 2017). "Besides the well-known MPM-associated genes, CDKN2A, NF2 and BAP1, other interesting cancer-associated genes were listed as frequently involved in a copy number loss (e.g. EP300, SETD2 and PBRM1)." (PMID 29371938, 2017). "Functional analysis based on the KEGG pathway database revealed that PBRM1 knockdown modulated key pathways, in particular cytokine/cytokine receptor interaction, focal adhesion, pathways in cancer, NOD-like receptor signaling pathway, and MAPK signaling pathway." (PMID 28846693, 2017). "The result suggests that PBRM1 may act differently through its regulation mechanisms in different cancer types." (PMID 27556922, 2016). "Still, the loss of VHL and increase in HIF transcriptional activity is not sufficient to cause or drive cancer, indicating that additional factors are required for promoting oncogenesis, including the mutation of epigenetic regulators such as PBRM1." (PMID 27100670, 2016). "BAF180 (also called PBRM1), a subunit of the SWI/SNF complex, plays critical roles in the regulation of chromatin remodeling and gene transcription, and is frequently mutated in several human cancers." (PMID 26992241, 2016). "Based on these new findings, intervention with PBRM1 expression and function may have its potential application in cancer therapy." (PMID 25978027, 2015). "It is significant that we observe PBRM1-dependent centromere fragility in the absence of any exogenous perturbation, suggesting that this fundamental feature of PBRM1 loss is a critical activity that contributes to tumourigenesis and cancer progression." (PMID 40011561, 2025). "Thus, H3K36me3 deregulation drives oncogenesis and metastasis in cancers beyond RCC, suggesting that SETD2's tumor/metastasis suppressor function is conserved among different tissues and independent of mutations commonly linked to ccRCC like VHL and PBRM1." (PMID 37418588, 2024). "However, consistent roles of PBRM1 loss-of-function mutations in patients with cancer or in cancer cell lines have not been determined." (PMID 39375538, 2024). "To the best of our knowledge, we are the first to have demonstrated that the PBRM1 IHC expression of endothelial cells is correlated with the expression of cancer cells, which suggests that the vascular endothelial cells may also be genetically or immunohistochemically abnormal." (PMID 35205810, 2022). "The specific mechanism underlying the association of decreased PBRM1 expression with the architectural patterns without a vascular network is still unclear, but the interaction of cancer cells and endothelial cells may be suggested." (PMID 35205810, 2022). "But mutations in PBRM1 alone did not cause ccRCC or other cancers." (PMID 34447697, 2021). "In recent years, large-scale cancer genomic projects have revealed numerous additional mutations in other tumor suppressors genes encoding chromatin remodelers, including protein polybromo 1 (PBRM1/BAF180), BRCA associated protein 1 (BAP1), and Set domain containing 2 (SETD2)." (PMID 30774762, 2019).
cancer (continued). "Interestingly, except for PBRM1, which showed a markedly high mutation frequency in kidney renal clear cell carcinoma (KIRC; 40.1%), most HAMPs showed mutation frequencies < 5% in a given cancer type." (PMID 30760718, 2019). "The aberrations of SMARCB1, SMARCA4, ARID1A, PBRM1, and SS18 within the SWI/SNF complex are frequently found in rare cancers and refractory cancers." (PMID 39625239, 2025). "To delve further into the impact of ALKBH1 mutations on STAD, we explored their interactions with other common genes involved in cancer progression, including TTN, PBRM1, and SETD2." (PMID 38317214, 2024). "After adjusting for cancer types and filtering out MSI-High samples, the POL&PBRM1 group had the highest signature scores in all response signatures (GEP: FDR < 0.001, IFG: FDR < 0.001, TLS: FDR = 0.088, TIS: FDR < 0.001, ICR: FDR < 0.001, CTL: FDR < 0.001)." (PMID 39218995, 2024). "Thus, PBRM1-BD4 missense variants may contribute to cancer pathogenicity by increasing nonspecific PBRM1 chromatin binding capacity." (PMID 38460939, 2024). "Moreover, investigating the clinical impact of AS alterations of PBRM1 E27, specifically targeting each cancer type, may provide a comprehensive understanding of cancer type-specific roles of PBRM1, providing a new biomarker to predict the therapeutic efficiency of immune checkpoint blockade." (PMID 39375538, 2024). "Family VIII inhibitors that are selective for PBRM1 bromodomains over those of SMARCA4 and SMARCA2 have also been developed and studied for anti-cancer effects." (PMID 38390898, 2024). "In the MSKCC cohort, after removing MSI-H patients and adjusting age, gender, and cancer types, the POL&PBRM1 group had the highest TMB value (P < 0.001)." (PMID 39218995, 2024). "Furthermore, by mapping cancer missense mutations across the protein sequence, which largely follows domain architecture, we found that, despite comprising only 6% of the overall protein sequence, the BD4 harbors 10% of all cancer-associated PBRM1 missense mutations." (PMID 38460939, 2024). "Additional investigations are needed to determine the specific alterations of PBAF complex functions according to AS alterations of PBRM1 or other mSWI/SNF family subunits in various cell types, including cells in cancer tissues." (PMID 39375538, 2024). "A recent study by Farnaby developed an optimized chemical ACBI1 that cooperatively targets SMARCA2, SMARCA4, and PBRM1, exhibiting significant antiproliferative and cell death-inducing effects in SMARCA4-mutant cancer cells." (PMID 36361605, 2022). "Importantly, the authors showed that PBRM1 mutations found in cancers failed to repress transcription nearby DSBs, thus suggesting that this function for PBRM1 may be associated with carcinogenesis or cancer progression." (PMID 36605718, 2022). "Seven top upregulated emRNAs and related to ccRCC or/and multiple malignant tumors, including CUL9, ATM, ARID1A, KMT2D, PBRM1, PREX2, and SETD2, were selected as candidate biomarkers for further testing." (PMID 36002886, 2022). "PBRM1 is a key component of the SWI/SNF chromatin-remodeling complex and it is widely considered as an oncosuppressor gene in various cancer types by virtue of its cell cycle regulation activity." (PMID 31212728, 2019). "Among eight HAMPs with M-scores > 0.4, EP300, PBRM1, and CREBBP had the largest overall M-scores across the 33 cancer types." (PMID 30760718, 2019). "Importantly, the dominant PBRM1 mutation category and type in KIRC and CHOL were truncating (83.9% and 85.7%, respectively) and homozygous (85.2% and 71.4%, respectively) mutations, which were remarkably higher than the averages in other cancer types (30.3% and 19.4%, respectively)." (PMID 30760718, 2019).